E2F1 (E2F transcription factor 1)
Diseases named in the same sentence as E2F1 in open-access papers (continued):
Sharing a sentence is not in itself a finding about the gene and the disease.
melanoma (continued). "Overexpression of a truncated E2F-1 protein lacking its transactivation domain failed to stimulate transcription from the PUMA promoter, suggesting that the transactivation domain is required for PUMA up-regulation in E2F-1-induced melanoma cell apoptosis." (PMID 17263886, 2007). "In conclusion, our results suggest that induction of the pro-apoptotic molecule PUMA and subsequent Bax activation contributes to E2F-1-induced apoptosis in melanoma cells." (PMID 17263886, 2007). "Taken together, these results suggest that PUMA up-regulation and Bax translocation play an important role in E2F-1-induced melanoma cell apoptosis." (PMID 17263886, 2007). "In melanoma, tranfection of the transcription factor E2F-1 induced apoptosis in the tumoral cell lines SK-MEL-28 and SK-MEL-2." (PMID 12838323, 2003). "Importantly, HMGCR expression in melanoma patients was positively correlated with E2F1 expression, suggesting the molecular axis in tumor cells that were observed in vitro hold true for cancer patients." (PMID 41339438, 2025). "A key epigenetic player in melanoma pathology is the E2F1 transcription factor." (PMID 39544930, 2024). "The simulations propose that IL-6 secreted by high-E2F1 melanoma cells is sufficient to trigger the activation of the IL-6/IL6R/STAT3 axis in CD4+ immune cells, which could also trigger secretion of other inflammatory factors." (PMID 39544930, 2024). "Here, we demonstrate that E2F1 is of outstanding importance for melanoma-immune cell communication." (PMID 39544930, 2024). "Thus, our findings indicate that AT-9283 safeguards the Rb-E2F complex by inhibiting Rb1 protein phosphorylation, thereby repressing the activity of transcription factor E2F-1 and blocking the G1-to-S phase transition in human melanoma A375P cells." (PMID 38474202, 2024). "Thus, our experimental setting provides a mechanistic model to derive the immune response in melanoma patients and emphasizes the prognostic and therapeutic benefit of disrupting the E2F1 and/or STAT3 coregulator interaction and its networks." (PMID 39544930, 2024). "Therefore, we examined the expression of both, E2F1 and IL-6, and mesenchymal or epithelial cell markers in aggressive melanoma cells, and analyzed their correlation." (PMID 39544930, 2024). "Beyond its physiological role as regulator of the cell cycle, metabolism, or tumor surveillance factor via apoptosis induction in response to DNA damage, abundantly high E2F1 expression stimulates metastatic transformation in melanoma and several other cancers." (PMID 39544930, 2024). "Using a comprehensive regulatory and functional map of E2F1 in tumor progression and metastasis which contains different types of regulatory factors, including genes, proteins, microRNAs, or complexes, we identified a core regulatory network in melanoma." (PMID 37993971, 2023). "Our approach supports the role of AKT1 and MDM2 protein signatures as drivers of EMT in melanoma cancer and suggests that MDM2 plus AKT1 inhibitors could be a promising combination for a novel anti-metastatic regimen in high E2F1-expressing melanoma patients." (PMID 37993971, 2023). "In support for a cause-effect relationship between GLI inhibition and the reduction in USP48 and iASSP mRNA levels, USP48 was found to be a direct transcriptional target of GLI1 in glioblastoma cells, and iASPP to be induced by GLI1/2 activation via E2F1 in melanoma cells." (PMID 35251038, 2022). "E2F1, therefore, can be considered as a potential new gold standard for melanoma metastasis." (PMID 36678712, 2022). "Interestingly, melanospheres derived from dex-stimulated parental (adherent) melanoma cells displayed a remarkable increase in stem cell markers (Oct3/4, AP-1, E2f1, Sox2 and NANOG), and that this increase was TDO-mediated." (PMID 35847038, 2022).
melanoma (continued). "A recent study also demonstrated that the downregulation of E2F1 in melanoma cells could induce cell senescence and cell death and further increase the sensitivity of melanoma cells to BRAF inhibitors." (PMID 34564711, 2021). "Interestingly, we found that the frequency of CNVs of E2F1 was higher in the patients compared to controls (4.5%), suggesting therefore that altered CNVs of E2F1 may play a key role as predisposing factor of BC as well as it was reported in patients with testicular cancer and melanoma." (PMID 33691613, 2021). "•Transcription factor E2F1 regulates ASAH1 expression in melanoma." (PMID 33766731, 2021). "miRNA-205-5p suppresses proliferation and induces senescence via regulation of E2F1 in melanoma." (PMID 32993558, 2020). "Stable SOX10 knockout reduces the level of E2F transcription factor 1 (E2F1) in melanoma cells." (PMID 33344444, 2020). "Given the role of E2F1 in melanoma progression and resistance to therapy, the authors also suggested that eugenol could be developed as an E2F-targeted agent for melanoma treatment." (PMID 32948083, 2020). "Furthermore, MDM2 relies on the regulation of transcription factor E2F1 to promote the invasion and motility of melanoma cells." (PMID 32964032, 2020). "miR-205 in melanoma cell lines inversely correlates with the expression levels of E2F1 and E2F5." (PMID 32722415, 2020). "Recent studies have demonstrated the existence of multiple copies of E2F1 gene in melanoma specimens which could explain the deregulated E2F1 activity in this type of cancer." (PMID 31142321, 2019). "Besides ETS1, we predicted AR, E2F1 and JUND as the most significant regulators in melanoma patients with a TERT promoter mutation." (PMID 31888467, 2019). "To understand whether the increased copy number of E2F1 gene impacted timing and site of melanoma manifestation, we collected the characteristics of the patients harbouring more than two copies of E2F1 gene." (PMID 31142321, 2019). "In conclusion, our studies suggest that targeting the E2F1 signaling pathway may be therapeutically relevant for melanoma." (PMID 29743521, 2018). "Recent study indicated that E2F1 was a potential transcription factor in melanoma." (PMID 30055641, 2018). "In addition, we observed that inhibition of E2F1 in melanoma cells leads to the presence of 53BP1 foci and increased γH2AX, two mediators recruited and phosphorylated at DNA-damaged sites." (PMID 29743521, 2018). "Here we confirmed that E2F1 is highly expressed in melanoma cells." (PMID 29743521, 2018). "Collectively, these data suggest that E2F1 is a critical mediator of melanoma drug sensitivity and may serve as an important target for novel therapeutic strategies." (PMID 29743521, 2018). "Altogether, these findings confirm that E2F1 is highly expressed in melanoma cells." (PMID 29743521, 2018). "Our studies suggest that targeting the E2F1 signaling pathway may be therapeutically relevant for treatment of melanoma patients." (PMID 29743521, 2018). "Inhibition of E2F1 increased the β-galactosidase activity of melanoma cells." (PMID 29743521, 2018). "Here, we report a key role for E2F1 in the control of melanoma cell death and drug sensitivity." (PMID 29743521, 2018).
melanoma (continued). "Second, we investigated whether E2F1 depletion acts synergistically with BRAF inhibitors to enhance its pro-apoptotic effect on melanoma cells." (PMID 29743521, 2018). "To assess whether E2F1 modulates the proliferation of melanoma cells, we developed two complementary approaches to inhibit E2F1 expression and/or activity." (PMID 29743521, 2018). "E2F1 and Cyclin D1 are highly expressed in melanoma cells and interrelated to each other." (PMID 29108247, 2017). "In addition, treatment of LY294002 on the cells blocked activation of PI3K/AKT, Cyclin D1 and E2F1 due to the knockdown of RGS4 in melanoma cells and consequently decreased the expression of p-Akt, Cyclin D1 and E2F1." (PMID 29108247, 2017). "In addition, eugenol was able to inhibit the E2F1 transcriptional activity and, as overexpression of E2F1 restores melanoma cell proliferation, this indicates that eugenol targets E2F functions in melanoma cells." (PMID 29258206, 2017). "In conclusion, for the first time we found that RGS4 expression was downregulated in melanoma tissues and cells which inhibited melanoma cell proliferation, migration and invasion due to the inactivation of Cyclin D1 and E2F1 via GPCR-mediated PI3K/AKT pathway." (PMID 29108247, 2017). "Moreover, E2F1 is expressed at considerably higher levels in metastatic than in primary tumors of melanoma patients." (PMID 26356814, 2015). "Indeed, we show that T-oligo increases E2F1 mRNA and protein levels as well as its DNA binding activity in human MM-AN melanoma cells, further confirming our previous finding that E2F1contributes to T-oligo effects." (PMID 20652008, 2010). "We sought to ascertain whether induction of PUMA plays a crucial role in E2F-1-induced apoptosis in melanoma cells." (PMID 17263886, 2007). "In addition, databases deposited in NCBI revealed that FANCA, FANCL, and probably FANCC genes were upregulated in E2F1-overexpressed SKMEL-2 melanoma cells." (PMID 19936073, 2007). "The purpose of this study was to identify whether PUMA up-regulation and Bax translocation contributed to E2F-1-induced apoptosis in melanoma cells." (PMID 17263886, 2007). "Loss of SOX10 in melanoma cells results in cell cycle arrest in the G1 phase, accompanied by molecular changes such as reduced MITF expression, elevated p21/WAF1 and p27KIP2 expression, hypo-phosphorylated RB, and reduced levels of E2F1; SOX10 is essential for melanogenesis." (PMID 38132479, 2023). "We demonstrate that heat stress could directly induce the mRNA expression of E2F1 in melanoma." (PMID 31142321, 2019). "Moreover, blocking E2F1 also induced death of melanoma cells resistant to BRAF inhibitors." (PMID 29743521, 2018). "Therefore, we hypothesized that RGS4 directly induced inactivation of E2F1 under the regulation of Cyclin D1 or AKT in melanoma." (PMID 29108247, 2017). "The authors, therefore, concluded that CDKN2A suppresses melanoma invasion by preventing the E2F1-mediated upregulation of BRN2, thereby identifying a key axis in melanoma progression." (PMID 41596618, 2026). "To determine the clinical relevance of the E2F1-HMGCR axis in the response to ICB therapy, we used the transcriptome data from melanoma patients classified as R or NR to anti-PD-1 therapy." (PMID 41339438, 2025).
melanoma (continued). "We show here that the histone reader ATAD2 is overexpressed in melanoma and predicts poor prognosis, and that the MAP kinase pathway, via the transcription factor E2F1, stimulates ATAD2 expression." (PMID 41331524, 2025). "In melanoma, miR-224/452-mediated downregulation of TXNIP is essential for E2F1-induced EMT and invasion." (PMID 38890620, 2024). "We performed iterative simulations modifying the values of E2F1 expression and found, that under basal STAT3 activation, increasing levels of E2F1 in melanoma cells can trigger the expression and secretion of IL-6." (PMID 39544930, 2024). "Nevertheless, E2F1-induced expression of IL6 and CD274, or elevated levels of STAT3, can mitigate the effect nurturing toward the Th2 direction in advanced stages of melanoma." (PMID 39544930, 2024). "It was postulated that H2A.Z.2 promote proliferation of melanoma cells by recruitment of Bromodomain-containing protein 2 (BRD2) and E2F1 to the promoter region of E2F target genes, where H2A.Z is known to occupy." (PMID 38542118, 2024). "IL-6 expression, driven by a newly identified interaction between endogenous E2F1 and active STAT3, leads to massive cytokine secretion via a positive feedback loop, both in melanoma and CD4+ T cells." (PMID 39544930, 2024). "Significantly weaker expression of the JARID1B, E2F1 and c-MYC genes was clearly seen in melanoma cells that overexpressed Pirin relative to the control cells." (PMID 37308689, 2023). "In regulating FAK signaling, RHAMM has also been reported to co-activate the E2F1 transcription factor to increase the transcription of fibronectin, which promoted integrin-β1-FAK induced motility in melanoma cells." (PMID 36033439, 2022). "Previously, it was demonstrated that H2AZ2 recruits E2F1 and BRD2 to the promoters of cell cycle genes to drive melanoma proliferation and invasiveness." (PMID 35058574, 2022). "In melanoma, it was proposed that H2AZ2 exerts its oncogenic function by recruiting E2F1 and BRD2 to the promoters of cell cycle genes." (PMID 35058574, 2022). "Here, using melanoma as a model, we show that TBX2 lies downstream from PI3K signaling and that TBX2 binds and is required for expression of E2F1, a key antisenescence cell cycle regulator." (PMID 34819350, 2021). "Collectively, these results show that the MAPK pathway increases E2F1 expression, which stimulates ASAH1 transcription in melanoma cells." (PMID 33766731, 2021). "Using melanoma as a model, they show that TBX2 lies downstream from PI3K signaling and that TBX2 binds and is required for expression of E2F1, a key antisenescence cell cycle regulator." (PMID 34819350, 2021). "In particular, the H2A.Z isoform H2A.Z.2 is highly expressed in melanoma and increases cell proliferation by recruiting BRD2 and E2F1 to E2F target genes." (PMID 32831131, 2020). "Further studies will be necessary to determine the respective contribution of E2F1 and E2F4 in the effects of HLM006474 in melanoma cells." (PMID 29743521, 2018). "We next carried out experiments to evaluate the effects of E2F1 blocking in combination with BRAF inhibitor, PLX4032, in BRAF inhibitor-resistant melanoma cells." (PMID 29743521, 2018). "Our data clearly indicate that E2F1 inhibition potentiates the anti-proliferative and pro-apoptotic effects of BRAF inhibitors, PLX4032 and dabrafenib, in melanoma cell lines sensitive to BRAF inhibitor." (PMID 29743521, 2018). "Further, treatment of GSPs also reduced the levels of pRbThr356, E2F1 and E2F2 proteins in melanoma cells which are the downstream targets of p21/WAF1/Cip1, and this effect of GSPs was dose-dependent." (PMID 25361006, 2014). "Up-regulation of the PUMA gene and protein by E2F-1 overexpression was detected by real-time PCR and Western blot analysis in the SK-MEL-2 melanoma cell line." (PMID 17263886, 2007).
melanoma (continued). "FANCA and FANCL mRNAs were clearly upregulated in E2F1 overexpressed SKMEL-2 melanoma cells, whereas FANCD1 and FANCG mRNAs were unchanged after E2F1 overexpression." (PMID 19936073, 2007). "More importantly, our data evidently supported a strong influence of E2F1 and its target IL-6 on the Th1/Th2 development like Th2 cytokine production, downregulation of ERK1/2 pathways, IFN-γ response (bottom), or CCL2 expression in melanoma cells." (PMID 39544930, 2024). "Overexpression of E2F1 has been demonstrated to be a negative prognostic factor for patient’s survival and, interestingly, its expression is higher in melanoma metastasis rather than in the primary tumor." (PMID 38794128, 2024). "Furthermore, our data point to a dynamic crosstalk between melanoma and CD4+ T cells leading to E2F1-dependent perturbations in the immunoregulatory transcriptome of both cell types." (PMID 39544930, 2024). "In addition, we demonstrated that the overexpression of Pirin in both the metastatic melanoma cell lines studied led to a significant decrease in JARID1B gene expression, and that of its target genes E2F1 and c-MYC30,31." (PMID 37308689, 2023). "However, in addition to G3BP1, KPNB1 can also play a role in cancer by regulating the nuclear transport of substrates, such as E2F transcription factor 1 (E2F1) and p65, which play a promoting role in melanoma." (PMID 35902727, 2022). "In addition, E2F1 regulates cell cycle gene transcription in a H2AZ- and BET bromodomain protein-dependent manner in melanoma and GBM." (PMID 35058574, 2022). "This upregulation likely occurs due to PI3K/AKT signaling activity, and targeting both E2F1 and IGF-1R may help to combat resistance in melanoma." (PMID 33807778, 2021). "To determine whether E2F1 regulates ASAH1 transcription, we knocked down E2F1 expression in the melanoma cell lines A375 and M14." (PMID 33766731, 2021). "Moreover, E2F1 and E2F5 were inversely correlated with miR-205 in melanoma cell lines as the expression of these two proteins was elevated in melanoma cell lines while miR-205 was found to be suppressed." (PMID 32854238, 2020). "This is the first study that shows a relation between germline E2F1 CNV and melanoma, suggesting that altered copies of this gene might be a predisposing factor to skin cancer." (PMID 31142321, 2019). "We used a melanoma cell line, SK-267-MEL, in order to determine whether environment insults such as heat stress may have an effect on the E2F1 expression." (PMID 31142321, 2019). "Given the pivotal role that E2F1 has in cell proliferation, its involvement in melanoma growth and progression is not surprising." (PMID 31142321, 2019). "Further, our experiments indicate that BRAF inhibitors do not increase the death induced by inhibition of E2F1 in melanoma cells resistant to BRAF inhibitors." (PMID 29743521, 2018). "In melanoma cells, HLM006474 induces similar effect as observed with specific E2F1 siRNA." (PMID 29743521, 2018). "Moreover, blocking E2F1 also induced death of melanoma cells resistant to BRAF inhibitors, and E2F1 inhibition increases sensitivity of melanoma cells to BRAF inhibitors." (PMID 29743521, 2018). "In this study, our results supported the hypothesis that RGS4 led to downregulation of Cyclin D1 and E2F1 expression via inactivation of the GPCR-mediated PI3K/AKT pathway, and as the results, inhibited melanoma cell growth, proliferation and so on." (PMID 29108247, 2017). "For example, deregulation of E2F1 enhanced invasion and metastasis of malignant melanoma without affecting proliferative activity." (PMID 26356814, 2015).